INS (insulin)
Diseases named in the same sentence as INS in open-access papers (continued):
Sharing a sentence is not in itself a finding about the gene and the disease.
Hepatic steatosis (continued). "IR, a defective response to insulin stimulation of target cells such as hepatocytes, skeletal muscle cells, and adipocytes, plays a crucial role in the development of several metabolic diseases including T2DM, obesity, metabolic dysfunction-associated fatty liver disease, and dyslipidemia." (PMID 38102588, 2023). "Thus, we hypothesize that celecoxib may effectively delay the progression of hepatic steatosis to advanced liver diseases in individuals with hepatic metabolic alterations induced by the insulin‐driven activation of PI3K/AKT/mTORC1 signalling in hepatocytes." (PMID 35713152, 2022). "Hypothesis was that hepatic insulin resistance (secondary to hepatic steatosis) via defective glucagon signaling/ glucagon resistance would lead to impaired ureagenesis and, hence, increased plasma concentrations of glucagonotropic amino acids and, subsequently, glucagon." (PMID 36686477, 2022). "The expression of fetuin-A and fetuin-B is both upregulated in the presence of hepatic steatosis in human, but their regulation of glucose homeostasis is different fetuin-A alters insulin signaling, while the fetuin-B mechanism may be related to glucose utilization." (PMID 36293317, 2022). "Hyperglucagonemia appears to be a pathophysiological consequence of hepatic steatosis, thus, the hypothesis of the study is that hepatic fat accumulation leads to increased insulin resistance and impaired glucagon metabolism leading to hyperglucagonemia in pediatric NAFLD." (PMID 36133310, 2022). "Furthermore, it is reported that the overexpression of either adiponectin receptor isoform in mouse liver is sufficient to improve ceramidase activity, total body glucose metabolism, and hepatic insulin sensitivity, while suppressing hepatic steatosis, in comparison to wild-type control animals." (PMID 35804799, 2022). "Furthermore, alcohol consumption could impair the insulin signaling pathway in the liver, leading to glucose and lipid metabolism disorders, becoming vital drivers of hepatic steatosis in ALD." (PMID 35464439, 2022). "Furthermore, a higher amount of MUFA and ALA in canola oil can exert beneficial effects against fatty liver by improving insulin sensitivity, glucagon-like peptide-1 responses, and up-regulation of glucose transporter-2 expression in the liver of insulin-resistant participants." (PMID 33514384, 2021). "When comparing normal and SCD1-knockout mice fed HFD, insulin sensitivity was enhanced, and lipid accumulation in the liver was reduced in the SCD1-knockout group, indicating that the deletion of Δ9 desaturase could help reduce insulin resistance and hepatic steatosis." (PMID 34007967, 2021). "Thus, improved WAT function combined with a substantial increase in plasma adiponectin levels may play a role in the potent effects of krill oil supplementation on both liver steatosis and insulin sensitivity in our mice with exacerbated NAFLD." (PMID 33572810, 2021). "Furthermore, a growing body of evidence from animal studies found that naringenin treatment resulted in an improvement in hepatic steatosis and metabolic parameters by reducing fasting plasma glucose, fasting plasma insulin, TG and TC levels in liver and plasma, and apoB-100 secretion." (PMID 34774104, 2021). "The reduction in both hepatic steatosis and hepatic gluconeogenesis would follow from improved iWAT insulin sensitivity and hepatic insulin sensitivity, respectively, which we demonstrated by the assessment of insulin-stimulated AKT phosphorylation in those tissues." (PMID 34083525, 2021).
Hepatic steatosis (continued). "In addition, it was observed that prebiotic feeding (e.g., with inulin-type fructans) strongly increased the presence of A. muciniphila and that this effect was correlated with lower obesity and fat mass, improved insulin resistance, lower liver steatosis and gut permeability." (PMID 34203876, 2021). "However, other studies indicated that liver steatosis is not always associated with insulin sensitivity." (PMID 34140896, 2021). "Moreover, palmitoleic acid contained in krill oil may contribute not only to the positive effects of this marine oil on glucose homeostasis and insulin sensitivity, but also on liver steatosis due to its stimulatory effects on PPARα and AMPK activation." (PMID 33572810, 2021). "Increased fructose intake has been shown to increase triglycerides, stimulate de novo lipogenesis, oxidative stress, and inflammation, and decrease hepatic insulin sensitivity, all of which may contribute to the development and progression of hepatic steatosis and MetS." (PMID 33061886, 2020). "Thus, MTTP deficiency does not alter hepatic or peripheral insulin action in young mice despite marked hepatic steatosis and increases in sn-1,2-DAGs in the lipid droplet fraction." (PMID 32907986, 2020). "Since the obese mice from the H-P7 group had significantly reduced liver steatosis along with the glucose and insulin responses, we thought this could be related to a total energy expenditure-related issue or that their liver parenchyma was improving its physiological activity." (PMID 32943651, 2020). "However, a reduction in insulin levels was found in patients with non-alcoholic fatty liver." (PMID 32824177, 2020). "This is because insulin increased hepatic steatosis could also elevate the ROS level." (PMID 33746742, 2020). "Insulin might aggravate hepatic steatosis and liver injury by inhibiting GLP-1R expression." (PMID 33746742, 2020). "In crossover comparisons between MD and a low-fat, high-carbohydrate diet, even without weight loss, MD reduces liver steatosis (assessed by magnetic resonance imaging) and improves insulin sensitivity in an insulin-resistant population with biopsy-proven NAFLD." (PMID 33053631, 2020). "During DPP4 deficiency (inhibition or a knockout in mice), the sensitivity of pancreatic β-cells to this hormone may diminish, and as a result, insulin secretion may decrease, which, along with the action of glucagon and fatty liver disease, raises blood glucose levels." (PMID 33228030, 2020). "Although ASAH2 may improve insulin sensitivity and hepatic steatosis and inhibits TNF-α-induced vascular inflammation, only a few studies have targeted the manipulation of ASAH2 expression as a therapeutic approach, as ASAH2 distribution and its functions remain unclear in many respects." (PMID 31817238, 2019). "Interestingly, even though the I148M variant predisposes patients to liver steatosis, it seems to not influence insulin sensitivity." (PMID 31010049, 2019). "Thus, fatty liver disease accompanied by elevated TP levels may reflect inflammation, which may affect the insulin signalling pathway in the liver and the whole body." (PMID 31315681, 2019). "Using chronic treatment with insulin and/or human chorionic gonadotropin (hCG), we showed that all female rats with different treatments induced imbalance between de novo lipogenesis and mitochondrial β-oxidation via the Pparα/β–Srebp1/2–Acc1 axis, resulting in varying degrees of hepatic steatosis." (PMID 29719598, 2018). "However, the detection of the hepatic insulin pathway sensibility could provide more valuable information to evaluate the insulin resistance in dairy cows with fatty liver." (PMID 29882814, 2018). "Importantly, the reduced GIP release observed in WD + WBE mice may be a protective mechanism in terms of reducing adipose tissue storage, hepatic steatosis and improving insulin sensitivity." (PMID 29549311, 2018).
Hepatic steatosis (continued). "However, three separate sets of primary outcomes were considered (insulin sensitivity, hepatic steatosis, subclinical chronic inflammation) and different mechanisms are discussed for the relevance of GI, GL or CHO from low- or higher-GI sources for these outcomes." (PMID 28604592, 2017). "Despite palmitoleate inducing hepatic steatosis, this FA may dissociate the liver inflammatory response from hepatic steatosis, and promote insulin-sensitization and its pro-lipogenic effect, by enhancing hepatic FAS expression due to higher expression of SREBP-1c." (PMID 29065507, 2017). "Therefore, pioglitazone could diminish the hepatic steatosis that is proportionally mediated by improving insulin sensitivity and enhancing lipophagy." (PMID 28831172, 2017). "The presence of hepatic steatosis and the inflammatory and pro-fibrogenic status in the liver of LDL-R−/− mice caused by the combined effects of fructose and the Western diet prompted us to examine the effects of the dietary interventions on the hepatic insulin signalling cascade." (PMID 28294959, 2017). "Given that ALT is a poor surrogate for liver disease (e.g., patients with advanced non-alcoholic liver disease may have normal circulating liver enzymes), imaging studies to quantify liver fat would have allowed us to more accurately evaluate the role of hepatic steatosis in insulin clearance." (PMID 27846285, 2016). "Therefore, although both HCD-fed and HFD-fed mice displayed hepatic steatosis, the difference in insulin sensitivity may be due to HCD preferentially inducing ChREBP, resulting in production of anti-inflammatory insulin-sensitizing lipids." (PMID 27992582, 2016). "Therefore, we asked whether VDD could promote endotoxemia, which consequently exerts systemic inflammation, leading to insulin resistance and hepatic steatosis." (PMID 27895587, 2016). "Together, these data confirm that both lowered insulin and leptin sensitivity occurred during the development of hepatic steatosis upon HFHS dieting, and suggest that the impairment in hepatic PI3K/Akt pathway may occur earlier than that in hepatic STAT3/SOCS3 pathway." (PMID 25658428, 2015). "Mice overexpressing DGAT2 did not have abnormalities of glucose tolerance or insulin levels, supporting the notion that hepatic steatosis may not necessarily be caused by insulin resistance." (PMID 26893932, 2015). "Similarly, improving insulin sensitivity can also lead to decreased hepatic steatosis in animals." (PMID 25658428, 2015). "The hypothesis that oxidative stress is causative in the development of metabolic disorders, especially insulin-resistant state, has been supported by different studies where treatments reducing ROS production improve insulin sensitivity, hyperlipidemia, and hepatic steatosis." (PMID 25143800, 2014). "We cannot exclude that longer exposure to HFD may have led to a higher degree of adipose tissue inflammation and hepatic steatosis, and, hence, myeloid-specific Fas deletion may have also influenced adipose tissue inflammation and/or hepatic insulin resistance." (PMID 24203314, 2014). "Our results indicate that choline restriction also triggers hepatic steatosis and hepatocellular injury during a nutritional state in which the mediators of de novo lipogenesis are transcriptionally silenced due to very high fat content in the diet and diminished circulating insulin concentrations." (PMID 24009777, 2013). "By the same means, the ARB agents improve insulin sensitivity and did not cause fatty liver." (PMID 23837919, 2013). "Thus, palmitoleate induces hepatic steatosis while improving liver insulin sensitivity." (PMID 22768070, 2012). "However, hepatic steatosis is seen in mice even at low insulin levels, suggesting that different mechanisms could regulate the induction of hepatic steatosis depending on the animal's physiological condition." (PMID 21869929, 2012).
Hepatic steatosis (continued). "Thus, palmitoleate supplementation could be useful for suppressing hepatic inflammatory response and for insulin-sensitization, but at a cost of inducing hepatic steatosis." (PMID 22768070, 2012). "Thus, our study indicates that the junction protein DSP, in synergy with insulin signaling, may be a novel target in the pathology of fatty liver disease." (PMID 22132232, 2011). "Thus, although chronic exogenous GH may reduce insulin sensitivity in rats fed a standard diet, it seems to reverse IR in an animal model of fatty liver induced by a high-fat diet." (PMID 20653983, 2010). "HCD-fed BALB/c mice showed elevated serum insulin (39.09 pg/dL ± 25.94), triglycerides (290.8 mg/dL ± 139.5), HOMA index (7.68 ± 1.49) and high post-challenge glucose along with visceral adiposity, hepatic steatosis, and pancreatic alterations." (PMID 41594843, 2026). "Compared with HFHC, both CAB and HECAB reduced serum insulin and HOMA-IR, attenuated hepatic steatosis, increased SOD1 and CAT, and reduced NF-κB, IL-6, TNF-α, and IL-1β, whereas GPx1 remained unchanged." (PMID 42193214, 2026). "miRNA-412 targets PLIN2, which plays an important role in the development of hepatic steatosis and inflammatory processes, while miRNA-216A modulates the expression of PTEN, a core regulator of insulin signaling, insulin resistance development, and apoptosis." (PMID 40869388, 2025). "In summary, hepatic steatosis in MASLD is supported by increased NEFA influx and de novo lipogenesis, with insulin signaling through IRS-1 and SREBP-1c and glucose metabolism-linked activation of ChREBP activation as key regulators." (PMID 41196673, 2025). "The treatment reduced hepatic steatosis and inflammation, lowered serum ALT, fasting glucose, and lipid levels, and improved insulin sensitivity." (PMID 41011683, 2025). "This suppression, resulting from impaired activity of the insulin‐degrading enzyme, leads to increased hepatic CD36 expression, which enhances the uptake of circulating free fatty acids and further aggravates hepatic steatosis." (PMID 40371883, 2025). "HFD FBXW7-FKO mice had ameliorated hepatic steatosis and serum lipid profiles compared to HFD WT, while their glucose and insulin sensitivity remained largely the same." (PMID 39747664, 2025). "Across studies, key parameters measured include liver steatosis (via histology), serum liver enzymes (ALT/AST), pro-inflammatory cytokines (e.g., TNF-α, IL-6), insulin resistance markers, and gut microbial composition." (PMID 41001122, 2025). "Participants in the highest TyG-BMI tertile (T3) exhibited elevated levels of FPG, HOMA-IR, TC, GGT, ALT, insulin, BMI, TG, and LDL, alongside increased risks of GDM and hepatic steatosis." (PMID 39962434, 2025). "In summary, MILK and YOG supplementation in the HFD model significantly lowered hepatic steatosis, consistent with changes in the abundance of enzymes that predict reduced DNL, enhanced β-oxidation, and improved insulin signaling in the liver." (PMID 40507838, 2025). "This trial showed a significant reduction in liver steatosis, measured with MRI‐PDFF compared to insulin Degludec." (PMID 39937036, 2025). "This miRNA reduces insulin sensitivity in hepatocytes by inhibiting insulin receptor substrate 1 and phospho-AKT, thereby exacerbating hepatic steatosis." (PMID 40001534, 2025). "Artificial light at night disrupts circadian and metabolic homeostasis, contributing to hepatic steatosis and the pathogenesis of MASLD through melatonin suppression, insulin resistance, and gut–liver dysregulation." (PMID 41302675, 2025). "Metabolites in such a pathway affect insulin function, while NAD helps to prevent diet‐induced hepatic steatosis." (PMID 40891122, 2025). "Taken together, these data strongly suggested although it was of minor importance for the progression of hepatic steatosis, a high level of hepatic ASPG exacerbated impairment of systemic insulin signal transduction." (PMID 40760121, 2025).
Hepatic steatosis (continued). "In a MASH mouse model, a ten-week IF intervention significantly reduced body weight, energy intake, and epididymal fat percentage, while alleviating hepatic steatosis, ballooning degeneration, lobular inflammation, NAFLD activity score, and insulin resistance." (PMID 40410852, 2025). "Specifically, miR-22 levels were negatively correlated with the expression of adipogenesis and insulin sensitivity markers in WAT, as well as the presence of liver steatosis." (PMID 40522819, 2025). "Although both MICT and HIIT reduce hepatic steatosis, HIIT often achieves more rapid and profound metabolic improvements, including improved insulin sensitivity and mitochondrial function." (PMID 40682843, 2025). "Third, the new nomenclature of metabolic-associated fatty liver disease has been recently suggested; however, this study could not apply this concept, as there was an absence of data on plasma high-sensitivity C-reactive protein and fasting insulin levels." (PMID 40093926, 2025). "It was shown that individuals in the T3 group tended to be older, have higher LDL-C, insulin, GGT, TC, FPG, TG, pre-pregnancy BMI, and a lower prevalence of grade 0 hepatic steatosis." (PMID 38414896, 2024). "In this sense, treatment of rats with sodium butyrate reduces plasma glucose levels, insulin resistance, fat accumulation in WAT, and liver steatosis, showing similar effects to an EE." (PMID 39000013, 2024). "Under standard chow feeding, these animals showed liver steatosis with decreased leptin and increased FFA, triglyceride levels, and hepatic glucose production compared with wild-type mice, though insulin sensitivity and glucose tolerance were comparable." (PMID 38727299, 2024). "Hepatic steatosis is triggered by a combination of elevated hepatic DNL rates, compromised glucose uptake in cells in response to insulin, and an excess of energy originating from FFAs via enhanced lipolysis of white adipose tissue." (PMID 39768947, 2024). "In mouse models of insulin–resistance treatment, FGF21 increased energy expenditure, reduced plasma circulating levels of glucose, improved liver steatosis, and improved both leptin and insulin sensitivity." (PMID 37274345, 2023). "Altogether, these data indicated that hepatocyte-specific deletion Bach1 improved insulin signaling and dysregulation of glucose homeostasis in HFD-fed mice, and protected from HFD-induced liver steatosis." (PMID 38129407, 2023). "↓BWG, FBG, insulin, HOMA-IR value, serum LPS, hepatic steatosis, adipocyte hypertrophy; ↑HDL-C level; ↓Ileum IL-6 and TNF-α levels; ↑↓Ileum IL-10 levels." (PMID 37396125, 2023). "When compared to other scores to detect hepatic steatosis, this score mainly includes AST, AST/ALT ratio, and fasting serum insulin level and is usually assessed as liver fat >5.56% (sensitivity, 86% and specificity, 71%)." (PMID 36769165, 2023). "Moreover, it was reported that alleviating liver steatosis could also improve insulin sensitivity." (PMID 37735236, 2023). "After drug withdrawal, the therapeutic effect of tamoxifen on hepatic steatosis was sustained for 4 weeks, however, the influence on other indicators such as serum TC, TG, HDL, and LDL levels and glucose and insulin tolerance gradually disappeared." (PMID 36864030, 2023). "Protein acetylation is a critical regulator of insulin sensitivity and metabolism, global SIRT1 overexpression can improve insulin sensitivity, glucose tolerance, and hepatic steatosis." (PMID 37143582, 2023). "While insulin signaling is known to promote lipid synthesis in the liver, reductions were seen in this study in the pathological grade of NASH, hepatic steatosis, fibrosis, and hepatocarcinogenesis in insulin-treated STAM mice when they were 20 weeks of age." (PMID 37852976, 2023). "We found that in the T3 group, participants generally had higher levels of pre-pregnancy BMI, LDL-C, TG, ALT, GGT, AST, insulin, HOMA-IR, and higher rates of grade 3 hepatic steatosis." (PMID 37576966, 2023).